MMP9 (matrix metallopeptidase 9)
Diseases named in the same sentence as MMP9 in open-access papers (continued):
Sharing a sentence is not in itself a finding about the gene and the disease.
tumor (continued). "MMP-9 expression was detected in the cytoplasm of tumor cells, while stromal cells were weakly positive for this marker; staining could be categorized as cytoplasmic or nuclear plus cytoplasmic." (PMID 25097794, 2014). "MMP-2 and MMP-9 can promote malignant cell progression and may facilitate the tumour growth, invasion and metastasis because of their ability to degrade type IV collagen of ECM and basement membrane." (PMID 24912879, 2014). "Furthermore, HSPB1 cleavage by MMP9 occurred during tumor progression and the anti-angiogenic HSPB1 fragment inhibited intratumoral MVD and tumor growth." (PMID 24465581, 2014). "Moreover, after application of MMP-2 inhibitor, the remaining gelatinase activity, corresponding to MMP-9, was highest in cancers with the most advanced degree of tumor infiltration." (PMID 24778099, 2014). "In the current research, no statistical association was detected between MMP-9 expression and patients’ age, tumor size, histological grade or HER2 status." (PMID 24993803, 2014). "The inhibition of MMP-9 expression might therefore be important in the development of a therapies for tumor metastasis." (PMID 24885456, 2014). "MMP-9 can be involved in the development of several human malignancies, as degradation of collagen IV in the basement membrane and the extracellular matrix facilitates tumor progression, including invasion, metastasis, growth and angiogenesis." (PMID 24476461, 2014). "The aim of this study was to measure the expression levels of MMP-2 and MMP-9 in the main tumor mass and in tumor cells on the positive margin and to compare these expression levels with Gleason score and tumor size in patients treated by radical prostatectomy." (PMID 25097794, 2014). "The expression of MMP-2 and MMP-9 is used to assess the ability of tumor aggressiveness." (PMID 24797571, 2014). "MMP9 then breaks down the extracellular matrix and allows tumor cell migration." (PMID 24827582, 2014). "MMP-9 is crucially involved in tumor cell invasiveness metastasis." (PMID 25421498, 2014). "A role for gelatinase B/MMP-9 has also been reported in the development of tumour tolerance." (PMID 24473089, 2014). "We also find that tumor cell-produced MMP-9 promotes tumor vascularization with only modest impact on primary tumor growth, and that silencing of MMP-9 expression in tumor cells leads to an altered transcriptional program consistent with reversion to a less malignant phenotype." (PMID 24811362, 2014). "MMP-9 can be involved in the development of several human malignancies, as degradation of collagen IV in basement membrane and extracellular matrix facilitates tumor progression, including invasion, metastasis, growth, and angiogenesis." (PMID 25136635, 2014). "Moreover, we, and others have shown that eHsp90 regulates the expression and activity of MMP-2 and MMP-9 in tumor cells." (PMID 24805867, 2014). "In addition, MMP9 and Ki67, markers of tumor invasion and proliferation were also suppressed by CCR10 shRNA." (PMID 25149529, 2014). "MMP9 promotes tumor migration, and inhibition of MMP9 can suppress tumor invasion and migration." (PMID 25057912, 2014). "Mechanisms that alter the equilibrium between gelatinase B/MMP-9 and its TIMP-1 inhibitor in favour of protease activity, facilitate gelatinase B/MMP-9 involvement in tumour pathology, and include differential expression, evasion from TIMP inhibition, and TIMP-1 inactivation." (PMID 24473089, 2014). "Knockdown of Hey1 decreased expression of MMP9 and attenuated tumor invasion." (PMID 24931473, 2014). "In addition, embelin inhibited the expression of markers of angiogenesis (COX-2, VEGF, VEGFR, and IL-8), and metastasis (MMP-2 and MMP-9) in tumor tissues." (PMID 24694877, 2014). "Interestingly, re-expression of Foxm1 in SPDEF-deficient tumor cells restored cell migration, coinciding with elevated levels of MMP2, MMP9 and MMP13." (PMID 25254494, 2014).
tumor (continued). "Neutrophils could promote tumor progression by producing proangiogenic factors such as Bv8, and MMP-9." (PMID 25587026, 2014). "Due to the positive contribution made by inflammatory cells to the metastatic process, inflammatory cell-derived gelatinase B/MMP-9 may promote extravasation, as may tumour cell derived gelatinase B/MMP-9." (PMID 24473089, 2014). "When we analyzed the correlation between the results for MMP-9 activation ratio obtained by zymography and active MMP-9 by immunohistochemistry for 32 matched cases of tumor, we found a positive relationship between zymography results and immunohistochemical scores (rs = 0.584, P < 0.001)." (PMID 24778099, 2014). "MMP-9 promotes vascularization of the tumor by upregulating the bioavailability of VEGF." (PMID 24944618, 2014). "Consistent with prior studies implicating MMP9 in angiogenesis and vasculogenesis, we also found that tumor cell-produced MMP9 was a significant contributor to the vascularization of the orthotopic tumors, although the impact of MMP9 knockdown on primary tumor growth was surprisingly modest." (PMID 24811362, 2014). "In particular, this cell surface hyaluronan receptor may promote tumor growth and metastasis serving as an anchor for matalloproteinase MMP9." (PMID 24921652, 2014). "Our data suggests that omega-3 PUFAs suppress MMP-9 induction and tumor angiogenesis." (PMID 24586907, 2014). "Gelatinase B/MMP-9 appears to be one of the genes required for tumor metastasis." (PMID 24473089, 2014). "To date, the functional role of tumor cell-produced MMP-9 has remained unclear." (PMID 24811362, 2014). "In addition to its normal physiological functions, MMP-9 (92 kDa collagenase IV) is involved in the development of several human malignancies and facilitates tumor progression, invasion, metastasis and angiogenesis." (PMID 24670365, 2014). "IFN-γ, but not TNF-α, could significantly reduce the expression of Bv8 and Mmp9 in the neutrophils from tumor-bearing mice and pG/pI6-mice, and abrogate the promoting effect of T-sMs on the expression of Bv8 and Mmp9." (PMID 25587026, 2014). "Indeed, the inhibition of gelatinase B/MMP-9 expression by inhibitors of pro-inflammatory cyclooxygenase-2 reduces tumour cell proliferation, invasion and metastasis." (PMID 24473089, 2014). "Similarly, the binding of pro-MMP-9 to the integrins αLβ2 and αMβ2 integrins induces the migration of human acute myeloid leukaemia (AML) cell lines and tumor-associated neutrophils." (PMID 24713998, 2014). "Further investigations revealed that MMP-9 and IDO may be implicated in SW1990 cell-induced NK cell dysfunction by facilitating tumor immune evasion." (PMID 25274283, 2014). "The MMP-9 (92 KDa) plays a crucial role in the mechanism of tumor invasion of many types of cancer." (PMID 25431779, 2014). "Increased tumor hypoxia is also associated with increased MMP-2 and MMP-9 activity." (PMID 23365550, 2013). "Similar results have been reported for MMP-9 levels in tumor tissue extracts." (PMID 24330623, 2013). "Our results were consistent with those from previous reports, and revealed that the inhibition of IL-17A expressed in tumor tissue significantly suppressed the microvessel density compared with a control model and was accompanied by lower expression of MMP9 and VEGF." (PMID 23372655, 2013). "In addition, MMP-9 is important for tumor metastasis by cleaving basement membranes, which allows migratory phenotype cells to be more invasive and motile." (PMID 23997800, 2013).
tumor (continued). "Using this model, investigators demonstrated that MMP-9 was expressed by neutrophils infiltrating the angiogenic islets and the tumors, while MMP-9-expressing macrophages were located along the periphery of the tumors, where tumor growth and angiogenesis occur." (PMID 23847541, 2013). "Additionally, however, acidic pHe both induces MMP-9 expression and enhances the rupture of protease-containing vesicles, hinting at acidosis driving tumor invasion." (PMID 24198789, 2013). "However, the function of the observed bleb structures and exactly how MMP-9 contributes to, and is activated and expressed during, tumor cell transendothelial migration remains unresolved and will form a subject for further investigation." (PMID 24194929, 2013). "Tumor-derived NO may also promote invasiveness through the induction of MMP-9 expression by tumor cells." (PMID 24325546, 2013). "Next, we examined the effects of ulinastatin on the expression of MMP-9 in tumor specimens." (PMID 23710449, 2013). "On the other hand, the expression of MMP9 was detected mainly in the cytoplasm of tumor cells." (PMID 23402362, 2013). "One study hypothesized that MMP-1 was involved in local invasion and that MMP-9 was involved in tumor growth and malignancy." (PMID 23696797, 2013). "Although tumor cells could be another source of MMP-9, we proved MMP-9 of mouse origin was down-regulated by IFN-α treatment." (PMID 23527047, 2013). "However, it has also been reported that FLNa is able to inhibit MMP-9 expression through Ras/MAPK/ERK signaling to affect tumor cell invasion." (PMID 24137390, 2013). "MMP-2, MMP-9, and other members of the MMP family have been associated with tumour progression." (PMID 23566419, 2013). "Targeting MMP9 by curcumin might serve as a potential therapeutic approach for tumor-induced angiogenesis and invasion." (PMID 24216994, 2013). "Similarly, higher protease activity for MMP-2 and MMP-9 was detected by zymography in tumor tissue compared to normal tissue." (PMID 23874773, 2013). "Furthermore, ACE inhibitors downregulate matrix metalloproteinases, MMP-2, and MMP-9 and inhibit tumor metastasis." (PMID 24223058, 2013). "MMP-9 expression did not correlate with age, gender, tumor location, or smoking habits, whereas an association with tumor grade differentiation and alcohol consumption was observed." (PMID 23365550, 2013). "In addition, tumor cells that stably express MMP-9 cDNA have been shown to have enhanced metastastic ability." (PMID 23407024, 2013). "We presumed that Gab1 might affect the biological behaviors of tumor cells by mediating VEGFR-2 via PI3K/Akt and could influence the invasion and metastasis of tumor cells via MMP-9." (PMID 24312291, 2013). "Although we have shown that EMMPRIN is required for the maximal induction of VEGF and MMP-9 in co-cultures of tumor cells with monocytes, it remains unclear whether the effect is mediated by the membranal or the soluble protein." (PMID 23874303, 2013). "In addition, other reports described that the expression of MMP-9 on immunosuppressive macrophages in the tumor microenvironment contributed to tumor invasion and metastasis." (PMID 23606867, 2013). "Moreover, the effects of lycopene are associated with the suppression of COX-2, prostaglandin E2 (PGE2), and ERK1/2 phosphorylation, which is inversely correlated with plasma levels of MMP-9 in tumour-bearing mice." (PMID 23970935, 2013). "Further, it was found that HSYA could inhibit the protein or mRNA expression of MMP-9 in tumor tissue to reduce the degradation of blood vessel membrane, restrain the migration of blood vessel and to decrease the tumor vascularization." (PMID 24335575, 2013). "In aggregate, these reports suggest that increased numbers of MMP-9+ cells around the tumor might be connected with CD163+ M2 macrophages and contribute to the poor prognosis of the tumor-bearing host." (PMID 23606867, 2013).
tumor (continued). "In addition, T1N0Mx-IgGs increased MCF-7 cell migration and invasion by up-regulating metalloproteinase-9 (MMP-9) activity in tumor cell supernatants." (PMID 23460876, 2013). "It was reported that Sp-1 mediates the transforming growth factor-β (TNF-β) stimulated EMT and cell migration, and also downregulates E-cad and upregulation of MMP-9, thereby loss of cell-cell contact resulting in EMT, which in turn results in tumor cell invasion and metastasis." (PMID 23970932, 2013). "The present study implied that withdrawal of IFN-α treatment may result in increased MMP-9 expression and macrophage infiltration in the lung and consequently more lung metastasis or tumor recurrence, which is consistent with our clinical studies." (PMID 23527047, 2013). "It is also noteworthy that other factors found locally in the tumor microenvironment could induce MMP-9 and VEGF." (PMID 23874303, 2013). "The SPARC and MMP9 are known to interact to regulate many stages of tumor progression." (PMID 23935929, 2013). "In addition, MMP2 and MMP9 enzymes play an essential role in cell-matrix interaction and tumor invasion and migration." (PMID 23382905, 2013). "Interestingly, our previous report also described the dense infiltration of CD163+ M2 macrophages and MMP9-bearing macrophage-like cells into the tumor, suggesting a contribution of M2 macrophages to the pathogenesis of AS." (PMID 24489574, 2013). "Furthermore, MMP-9 was previously shown to play a critical role in maintaining the tumor microenvironment, leading to enhanced cancer cell motility and cancer growth." (PMID 23941575, 2013). "It has been reported that expression of MMP-9 closely correlates with tumor angiogenesis." (PMID 23383216, 2013). "Furthermore, the high stromal expressions of uPA and MMP-9 in aggressive tumours suggest that these molecules are potential therapeutic targets in the post-operative treatment of canine mammary cancer." (PMID 23289974, 2013). "MMP9, also known as 97 kDa type IV collagenase, plays important roles in tumor invasion." (PMID 24236052, 2013). "In that study conducted in Poland, MMP1 was associated with node- negative breast cancer, whereas MMP9 was associated with ER−/PR− tumors, greater lymph node involvement, and larger tumor size." (PMID 23696797, 2013). "Overexpression of CD44s (d and d') and MMP9 (f and f') was clearly observed in tumor cells." (PMID 23476138, 2013). "In addition, knockdown of p38 MAPK, either by chemical inhibition or siRNA, decreased the expression of MMP9 and the ability of tumor cells to migrate." (PMID 23799978, 2013). "As before, the co-incubation of the A498 or the MCF-7 tumor cells with the U937 monocytic cell line in a mixture that allows cell–cell contact resulted in increase of both MMP-9 and VEGF in the supernatants, whereas the separate incubation of the cells in the inserts did not change this effect." (PMID 23874303, 2013). "Additionally, the expression of MMP-9 by CD11b+ myelomonocytes was necessary for vascular restoration and tumor growth in irradiated tissues." (PMID 23882218, 2013). "N-acetyl cysteine has been shown to modulate MMP-9 and invasive activities of tumor cells." (PMID 23446555, 2013). "Moreover, the expression of MMP9 in human CRC tumor samples significantly correlated with the PlGF expression levels in the samples, as well as the PlGF expression and Flt-1 expression." (PMID 23799978, 2013). "A significant correlation was established only between MMP-9/TIMP-1 activities with the tumor size." (PMID 23672427, 2013). "Our present study showed that IFN-α preconditioned lung, associated with reduced MMP-9 expression, is not a promising site for the incoming tumor cells." (PMID 23527047, 2013). "Overexpression of E-cadherin in highly invasive cells may reduce tumor cell invasiveness by decreasing MMP-9 and MMP-2 expression." (PMID 23870199, 2013).
tumor (continued). "Taken together, our current knowledge of MMP-9 has been extended; it can act as either a carcinoma protector or promoter depending on the specific situation, which is related to patient characteristics, including the stage, grade, and location of the tumor." (PMID 23365550, 2013). "The tumor microenvironment matrix expresses and sequesters MMP-9." (PMID 23365550, 2013). "Indeed, MMP-9 produced by tumor infiltrating myeloid cells, including TAMs, or bone marrow (BM) cells is crucial for tumor angiogenesis and progression." (PMID 24314323, 2013). "MMP-2 and MMP-9 mRNA expression increased significantly with the TNM stage of the tumor." (PMID 23281640, 2013). "Both MMP-2 and MMP-9 are involved with the invasive metastatic potential of tumor cells." (PMID 23764122, 2013). "MMP-9 has a more specific role in pathological remodeling, and gene regulation may be specific to the tumour region." (PMID 22593690, 2012). "Furthermore, they not only secrete cytokines, such as VEGF, MMP9, and TGFβ, to support angiogenesis in tumors, but also serve directly as precursors to form tumor endothelium in vivo, which facilitates tumor growth and tumor invasion." (PMID 23173040, 2012). "Overexpression of MMP9 in tumours led investigators to question whether measurement of serum levels may provide a useful diagnostic test." (PMID 22433968, 2012). "Thus, high CD3, CD20 or CD68 counts were significantly associated with MMP-9 expression, at the invasive front; whereas high CD68 count was significantly associated with MMP-14 and TIMP2 in this same tumor location." (PMID 23300781, 2012). "We hypothesize that enhanced levels of both, MMP-2 and MMP-9 accelerate disruption of the basement membrane and degradation of the dermal equivalent, both events that resemble tumor invasion in vivo." (PMID 22792213, 2012). "Recent findings suggest possible mechanisms underlying lipocalin-2 function in tumorigenesis, such as promoting the epithelial-mesenchymal transition (EMT), regulating the iron homeostasis in cancer cells, affecting on steroid-dependent tumor growth and modulating MMP-9 activity." (PMID 22640376, 2012). "As IL-23p19 knockout mice were reported to have decreased MMP9 expression, which played an important role in tumor metastasis, we studied whether IL-23 influenced HCC MMP9 expression or not." (PMID 23050001, 2012). "Indeed, it has been previously reported that CD82 suppresses tumor invasion by MMP9 inactivation via TIMP1 up-regulation in carcinoma cell line." (PMID 22679510, 2012). "In addition to being important in EMT and tumor invasion, snail also plays a role in embryonic development and it also influences apoptosis, angiogenesis and MMP9 expression, factors which are all important in tumor growth." (PMID 23157169, 2012). "Overall, TCTP-1 tumor uptake was low, with weak correlation to MMP-9 expression in melanoma tumors." (PMID 23201642, 2012). "The MMP-9 expression may be closely related to proliferation, invasion, and metastasis of tumour cells, and even to tumour angiogenesis." (PMID 23107277, 2012). "In addition, levels of MMP-2 and MMP-9 expression in xenograft tumor sections confirmed the in vitro data." (PMID 22681957, 2012). "MMP2 and MMP9 were abnormal in 18 (9%) and 38 (19%) of the tumours, respectively." (PMID 23304558, 2012). "The reduction of S100A4 and MMP9 was confirmed by immunohistochemistry of tumor tissue samples." (PMID 22878175, 2012). "MMP9-induction by AXL enhances the invasive capability of tumor cells." (PMID 22570691, 2012). "N-acetylcysteine has been shown to modulate MMP-9 and the invasive activities of tumor cells." (PMID 23007964, 2012). "Several studies have recently shown that neutrophils can synthesize a large number of serine proteinases, such as neutrophil elastase (NE), cathepsin G, proteinase-3, metalloproteinase 8 (MMP-8), and MMP-9, which alter the tumor microenvironment and promote tumorigenesis." (PMID 23272179, 2012).